FAM111A (FAM111 trypsin like peptidase A)
Description:
Single-stranded DNA-binding serine protease that mediates the proteolytic cleavage of covalent DNA-protein cross-links (DPCs) during DNA synthesis, thereby playing a key role in maintaining genomic integrity. DPCs are highly toxic DNA lesions that interfere with essential chromatin transactions, such as replication and transcription, and which are induced by reactive agents, such as UV light or formaldehyde. Protects replication fork from stalling by removing DPCs, such as covalently trapped topoisomerase 1 (TOP1) adducts on DNA lesion, or poly(ADP-ribose) polymerase 1 (PARP1)- DNA complexes trapped by PARP inhibitors. Required for PCNA loading on replication sites. Promotes S-phase entry and DNA synthesis. Also acts as a restriction factor for some viruses including SV40 polyomavirus and vaccinia virus. Mechanistically, affects nuclear barrier function during viral replication by mediating the disruption of the nuclear pore complex (NPC) via its protease activity. In turn, interacts with vaccinia virus DNA-binding protein OPG079 in the cytoplasm and promotes its degradation without the need of its protease activity but through autophagy.
Synonyms: KIAA1895; FLJ22794; GCLEB; KCS2
Tractability: PROTAC: UniProt records ubiquitination sites on it; ubiquitination databases record sites on it.
Gene: Protein-coding gene on chromosome 11 (59,142,703 to 59,155,042, forward strand). Ensembl gene ENSG00000166801.
Subcellular location: Nucleus; Chromosome; Cytoplasm
Subcellular location (Human Protein Atlas): Nucleoli fibrillar center; Nucleoplasm
Gene Ontology:
Molecular function: protein binding; single-stranded DNA binding; serine-type peptidase activity
Biological process: DNA damage response; DNA replication; negative regulation of viral genome replication; protein autoprocessing; protein-DNA covalent cross-linking repair; proteolysis; replication fork processing
Cellular component: chromatin; chromosome; cytoplasm; nucleus
Genetic constraint (gnomAD): Loss-of-function variants: 1 observed, 1.03 expected, observed/expected ratio (o/e) 0.97, 90% interval 0.26 to 1.89. That is too few expected variants to judge how well the gene tolerates losing a copy. Missense variants: 655 observed, 732.95 expected, observed/expected ratio (o/e) 0.89, 90% interval 0.84 to 0.95. Synonymous variants: 221 observed, 247.43 expected, observed/expected ratio (o/e) 0.89, 90% interval 0.8 to 1.
Gene-disease validity (ClinGen):
ClinGen rates the evidence that FAM111A causes each of these diseases.
FAM111A-related skeletal dysplasia (autosomal dominant): Definitive. Any skeletal dysplasia in which the cause of the disease is a variation in FAM111A gene.
Homologues: Orthologues: chimpanzee FAM111A (97% identical), macaque FAM111A (90% identical), rabbit FAM111A (67% identical), dog FAM111A (63% identical), mouse Fam111a (57% identical), rat Fam111a (57% identical), guinea pig FAM111A (54% identical), mouse A330040F15Rik (51% identical), pig FAM111A (51% identical), rat Fam111al1 (46% identical), zebrafish fam111.2 (15% identical). Paralogues in human: FAM111B (36% identical).
Diseases named in the same sentence as FAM111A in open-access papers:
FAM111A is named in the same sentence as 50 diseases in open-access papers, as found by Europe PMC text mining. Sharing a sentence is not in itself a finding about the gene and the disease. The quoted sentences say what the papers report.
osteocraniostenosis (14 papers, 2015 to 2025). A lethal skeletal dysplasia characterized by a cloverleaf skull anomaly, facial dysmorphism, limb shortness, splenic hypo/aplasia and radiological anomalies including thin tubular bones with flared metaphyses and deficient calvarial mineralization. "Heterozygous gain-of-function variants in FAM111A cause skeletal dysplasias, such as the perinatal lethal osteocraniostenosis and the milder Kenny-Caffey syndrome (KCS)." (PMID 39501122, 2025). "Heterozygous mutations in FAM111A gene have been found in patients with osteocraniostenosis (OCS, also known as gracile bone dysplasia, MIM 602361) as well." (PMID 38591167, 2024). "Dominant missense mutations in the human serine protease FAM111A underlie perinatally lethal gracile bone dysplasia and Kenny–Caffey syndrome, yet how FAM111A mutations lead to disease is not known." (PMID 32776417, 2020). "FAM111A and FAM111B dysregulation are linked to genetic disorders: Kenny–Caffey Syndrome type 2 and Gracile Bone Dysplasia for FAM111A and POIKTMP, respectively, and cancers." (PMID 38474092, 2024). "FAM111A gene mutations cause Kenney–Caffey syndrome (KCS) and Osteocraniostenosis (OCS), conditions characterized by short stature, low serum ionized calcium (Ca2+), low parathyroid hormone (PTH), and bony abnormalities." (PMID 38697929, 2024). "In humans, heterozygous point mutations in FAM111A are linked to two severe developmental syndromes: the Kenny–Caffey syndrome (KCS2, OMIM-127000) and Gracile bone dysplasia (GCLEB, OMIM-602361)." (PMID 37793778, 2023). "By contrast, heterozygous missense variants in a restricted region of the FAM111A gene have been identified in autosomal dominant type 2 KCS (KCS2) and a more severe lethal phenotype, osteocraniostenosis (OCS); these variants have recently been shown to confer a gain of function." (PMID 39932783, 2025). "This domain is 45 % homologous to the one predicted in FAM111A [MIM 615292], in which causative mutations have been recently reported to cause the Kenny-Caffey syndrome (KCS [MIM 127000]) and osteocraniostenosis (OCS [MIM 602361]), two clinical entities phenotypically distinct from POIKTMP." (PMID 26471370, 2015). "Functional homology between FAM111A and FAM111B has been reported, however FAM111A dominant missense variants give rise to very different clinical phenotypes without dermatological involvement, such as Kenny-Caffey syndrome type 2 (MIM: 127000) and Gracile bone dysplasia (MIM: 602361)." (PMID 40840166, 2025). "Mutations within the FAM111A gene have been identified as the genetic basis for two related disorders: Kenny–Caffey Syndrome type 2 (KCS2) and the more severe Gracile Bone Dysplasia (GCLEB), also known as osteocraniostenosis (OCS)." (PMID 38474092, 2024). "FAM111A gene heterozygous point mutations are associated with two severe developmental syndromes: KCS2 (OMIM #127000) and Gracile bone dysplasia/Osteocraniostenosis (GCLEB/OCS, OMIM #602361)." (PMID 39797201, 2024).
hypoparathyroidism (6 papers, 2018 to 2024). Hypoparathyroidism is an endocrine disorder in which the parathyroid glands in the neck do not produce enough parathyroid hormone (PTH). "While hypoparathyroidism is a common feature of KCS2, the PTH concentration in the serum of Fam111a−/− animals was similar to that in the Fam111a+/+ group." (PMID 35715480, 2022).
Kenny-Caffey syndrome type 2 (5 papers, 2016 to 2025). "Mutations in Hbb have been implicated in a number of blood disorders, while mutations of Fam111a are strongly associated with type 2 Kenny-Caffey syndrome." (PMID 27993158, 2016). "Finally, ES revealed two additional alterations in individuals with syndromic CS–p.Arg1295* in the MN1 (P63), which was recently discovered, and subsequently linked to CS, and p.Arg305Gly in FAM111A (P136), resulting in Kenny-Caffey syndrome type 2, in which CS represents an unseen clinical feature." (PMID 35591945, 2022).
22q11.2 deletion syndrome (2 papers, 2021 to 2023). 22q11.2 deletion syndrome (DS) is a chromosomal anomaly which causes a congenital malformation disorder whose common features include cardiac defects, palatal anomalies, facial dysmorphism, developmental delay and immune deficiency. "Although 22q11.2 deletion syndrome and chromosomal abnormalities were ruled out in this case, a genetic etiology could not be ruled out as the patient was not evaluated for other genetic abnormalities such as NEBL, TBCE, FAM111A, CASR, and GNA11 mutations." (PMID 36865979, 2023).
Hypomagnesemia (2 papers, 2017 to 2023). An abnormally decreased magnesium concentration in the blood. "In humans, FAM111A variants are associated with hypomagnesemia and renal Mg2+ wasting, consistent with the phenotype observed in LM/Bc mice." (PMID 37377737, 2023). "Human GOF variants in FAM111A are associated with hypomagnesemia and hypermagnesuria, but exactly how FAM111a is involved in regulation of renal Mg2+ transport is not clear." (PMID 37377737, 2023). "FAM111A is the only gene in this group of which the pathophysiological mechanism underlying the hypomagnesemia has received no attention at all." (PMID 27234911, 2017).
immune deficiencies (2 papers, 2019 to 2025). "Our work confirms and extends the recent case report of 2 siblings with immune deficiency and KCS2 who were compound heterozygotes for FAM111A variants (c.976T>A; p.L326I and in-frame deletion variant c.1714_1716del; p.Ile572del, rs779963813)." (PMID 39932783, 2025).
prostate carcinoma (2 papers, 2025). A carcinoma that arises from epithelial cells of the prostate gland. "•The AR represses FAM111A protease transcription in multiple castration sensitive and resistant prostate cancer cells." (PMID 40446667, 2025). "Two recently published studies identified several genes—BIK, SAMHD1, FAM111A, AOX1, among others—in which rare variants are significantly and strongly associated with increased risk of prostate cancer (PCa) and its aggressiveness." (PMID 40825105, 2025).
viral infection (2 papers, 2022). "Future studies on FAM111A’s role as a host restriction factor will provide mechanistic insight into defense mechanisms human cells use to fight viral infections." (PMID 36589246, 2022).
gastric cancer (1 paper, 2023). A primary or metastatic malignant neoplasm involving the stomach. "When the eight characteristic genes (ENTPD3, PDZD4, CNN1, GTPBP4, FPGS, UTP25, CENPW, and FAM111A) are all fitted into one variable, the AUC of the ROC curve is 0.996, indicating a good diagnostic efficiency for gastric cancer." (PMID 37007099, 2023). "We have established the early diagnosis model of eight characteristic genes (ENTPD3, PDZD4, CNN1, GTPBP4, FPGS, UTP25, CENPW, and FAM111A) for gastric cancer." (PMID 37007099, 2023).
glioma (1 paper, 2020). A benign or malignant brain and spinal cord tumor that arises from glial cells (astrocytes, oligodendrocytes, ependymal cells). "FAM111A expression was closely related to the malignant phenotype, molecular pathology and immune response of lower-grade glioma." (PMID 33194678, 2020). "Compared to WHO grade II gliomas in the CGGA dataset, WHO grade III gliomas showed a higher mRNA expression of FAM111A." (PMID 33194678, 2020). "We aim at investigating the expression and function of FAM111A in lower-grade glioma at the molecular and clinical levels." (PMID 33194678, 2020). "We found that FAM111A was indeed highly elevated in IDH wild-type gliomas in both of the CGGA and TCGA data sets." (PMID 33194678, 2020). "Taken together, these results suggest that FAM111A was significantly up-regulated in WHO grade III gliomas." (PMID 33194678, 2020). "The FAM111A protein expression was also higher in high-grade gliomas and IDH wild-type gliomas." (PMID 33194678, 2020). "The results showed that the FAM111A protein expression was higher in high-grade gliomas." (PMID 33194678, 2020). "However, the detail of FAM111A expression and its role in glioma are still unknown." (PMID 33194678, 2020). "In this research, we assessed the expression patterns of FAM111A to determine its potential functions and prognostic values in LGG based on data from the Chinese Gliomas Genome Atlas (CGGA) and The Cancer Genome Atlas (TCGA) datasets." (PMID 33194678, 2020). "FAM111A expression was overexpressed in WHO grade III and IDH-wildtype lower-grade glioma." (PMID 33194678, 2020). "High expression of FAM111A predicted a remarkably shorter overall survival (OS) both in CGGA and in TCGA datasets in LGGs, which included WHO grade II and WHO grade III gliomas." (PMID 33194678, 2020).
hepatocellular carcinoma (1 paper, 2024). A malignant tumor that arises from hepatocytes. "Recently, long noncoding RNA (lncRNA) of FAM111A (known as FAM111A-divergent transcript or FAM111A-DT) have been shown to promote the progression and poor survival rate of hepatocellular carcinoma (HCC) through its modification by N6-methyladenosine (m6A)." (PMID 38474092, 2024).
Hypermetropia (1 paper, 2024). An abnormality of refraction characterized by the ability to see objects in the distance clearly, while objects nearby appear blurry. "In KCS2 patients with the FAM111A gene p.R569H pathogenic variant, the most common ocular finding is hypermetropia, whereas tortuous optic nerves, as in our proband, have never been described (to our knowledge)." (PMID 39797201, 2024).
hypogonadism (1 paper, 2024). A disorder characterized by decreased function of the gonads. "Microorchidism and hypogonadism with increased FSH levels have been described in male patients with KCS2 and the FAM111A gene p.R569H pathogenic variant." (PMID 39797201, 2024).
osteopetrosis (1 paper, 2024). Osteopetrosis, also known as marble bone disease, is a descriptive term that refers to a group of rare, heritable disorders of the skeleton characterized by increased bone density on radiographs. "We found that genes associated with osteopetrosis have undergone positive selection (CSF1R and LRRK1) or pseudogenized (FAM111A and IGSF23) in the African manatee, potentially contributing to the dense bone formation." (PMID 39092175, 2024).
osteosarcoma (1 paper, 2025). A usually aggressive malignant bone-forming mesenchymal neoplasm, predominantly affecting adolescents and young adults. "To address whether the recessive Y414C variant in FAM111A causes KCS2 by a similar GoF effect, we generated a panel of human U2OS osteosarcoma cell lines conditionally expressing different GFP-tagged patient-associated FAM111A alleles or FAM111AWT at comparable, near-endogenous levels." (PMID 39932783, 2025).
parathyroid disease (1 paper, 2025). "Among these, several genes such as APC, CEP152, CREBBP, FAM111A, FGFR1, KL and MMP14 have been previously suggested to be associated with parathyroid disease." (PMID 40434298, 2025).
ZIKV infection (1 paper, 2021). "Although FAM111A and RFC3 act as nuclear localization-related factors and both played important role in DNA virus replication, whether they are involved in RNA virus such as ZIKV infection remains to be determined." (PMID 34930359, 2021).
cancer (6 papers, 2020 to 2025). A tumor composed of atypical neoplastic, often pleomorphic cells that invade other tissues. "In the HAP1 cancer cell line, FAM111A knockout causes cell cycle abnormalities and increased apoptotic cell death after treatment with DPC-inducing chemicals." (PMID 39501122, 2025). "Since these binding sites would not be conserved on other proteases, it would provide an opportunity for developing an inhibitor that is specific to FAM111A with the potential to enhance cancer therapeutic efficacy as well as treat disease caused by FAM111A misregulation." (PMID 38453899, 2024). "FAM111A knockdown in the U2OS cancer cell line and in human TIG-3 primary lung fibroblasts reduces the DNA replication rate and cell proliferation." (PMID 39501122, 2025). "Even in cancer cell lines, different cellular effects have been observed upon FAM111A knockdown or knockout." (PMID 39501122, 2025). "Another possible explanation is that FAM111B/FAM111A-repair machinery confers some advantage to cancer cells at later stages of cancer, thus supporting cancer progression." (PMID 35860584, 2022). "Altogether, our findings reveal a role of FAM111A in overcoming protein obstacles to replication forks, shedding light on cellular responses to anti-cancer therapies." (PMID 32165630, 2020). "This study not only sets new frameworks for future studies on DPC repair, replication fork regulation, and anti-cancer therapies, but also provides new insight into the role of FAM111A in genetic diseases and viral defense mechanisms." (PMID 32165630, 2020). "FAM111A inhibitors could also be used to sensitize cells to DPC-inducing drugs or to enhance their efficacy in cancer cells where alternative pathways of DPC bypass and repair are missing or inhibited." (PMID 38453899, 2024). "Moreover, our data showed that FAM111A levels vary among cancer cell lines." (PMID 32165630, 2020).
genetic disorders (5 papers, 2020 to 2024). "FAM111A mutations have been implicated in genetic disorders like Kenny–Caffey Syndrome type 2 (KCS2) and Gracile Bone Dysplasia (GCLEB)." (PMID 38474092, 2024). "Mutations in the FAM111B gene also lead to a genetic disorder, but the phenotypes are distinct from disorders with FAM111A mutations." (PMID 36589246, 2022). "Although cellular functions of FAM111A remain relatively uncharacterized, studies in the past 10 years have implicated FAM111A in antiviral defense, DNA replication, and genetic disorders." (PMID 36589246, 2022). "FAM111A is mainly associated with various functions such as antiviral defense, DNA replication and genetic disorders, but its precise role in these diseases is still not fully understood." (PMID 38474092, 2024). "Furthermore, heterozygous missense mutations in FAM111A and FAM111B cause distinct genetic disorders." (PMID 36589246, 2022).
infection (3 papers, 2012 to 2025). The state of being infected such as from the introduction of a foreign agent such as serum, vaccine, antigenic substance or organism. "In addition, RNAi-mediated knockdown of FAM111A levels in restrictive cells restored lytic infection of SV40 host range mutants and human adenovirus." (PMID 23093934, 2012).
skeletal dysplasia (2 papers, 2024 to 2025). Any Mendelian diseases that affects growth and development of the skeleton. "Based on our results and published data, we hypothesize that loss of FAM111A and FAM111A protease hyperactivity, as observed for gain-of-function patient-variant proteins, may converge on a similar pathomechanism underlying skeletal dysplasias." (PMID 39501122, 2025).
tumor (2 papers, 2020 to 2025). "Functional characterization of FAM111A revealed that it was associated with inflammatory response and immune response to tumor cells." (PMID 33194678, 2020). "What’ more, we performed the immunohistochemistry (IHC) to explore the relation between tumor grade, and FAM111A protein expression." (PMID 33194678, 2020). "Taken together, it is most likely that FAM111A played a critical role in the tumor immunity and may act as an immune suppressor in LGGs." (PMID 33194678, 2020). "Transcriptional studies that assessed gene expression in primary PCa, tumor-adjacent tissue and metastatic lesions Gene Expression Omnibus (GEO) Accession GSE6919 revealed that FAM111A expression is higher in primary PCa and tumor-adjacent tissue than in metastatic lesions." (PMID 40446667, 2025). "Interestingly, the C4 with high-expression FAM111A expression group was also related to the MHCs and immunostimulators, which might indicate the activation of the interferon gamma response pathway and a more complex relationship between FAM111A and tumor immunity in LGGs." (PMID 33194678, 2020).
FAM111A also shares sentences with these, for which no sentence is quoted: Intellectual disability (4 papers); Hypocalcemia (3); Kenny-Caffey syndrome (2); microcephaly (2); APECED) syndrom (1); autoimmune disease (1); B-cell non-Hodgkin lymphoma (1); Bartter syndrome type 3 (1); Bartter syndrome type 4 (1); blood disorders (1); eosinophilia (1); Gitelman syndrome (1); hair diseases (1); hearing loss (1); Hepatitis (1); Hyperglycemia (1); hyperuricemia (1); hypothyroidism (1); Insulin resistance (1); Macrocephaly (1); medulloblastoma (1); Micropenis (1); nanophthalmos (1); neutropenia (1); oral disorders (1); pediatric germ cell tumors (1); Sanjad-Sakati syndrome (1); steatosis (1).